RN7SKP252 (RN7SK pseudogene 252)
Gene: Miscellaneous RNA gene on chromosome 22 (49,738,677 to 49,739,003, forward strand). Ensembl gene ENSG00000223142.
Homologues: Orthologues: chimpanzee 7SK (98% identical), mouse Gm56005 (54% identical). Paralogues in human: RN7SKP184 (67% identical), RN7SKP47 (66% identical), 7SK (66% identical), RN7SKP187 (66% identical), RN7SKP50 (65% identical), RN7SKP78 (65% identical), RN7SKP79 (65% identical), RN7SKP86 (65% identical), RN7SKP48 (64% identical), RN7SKP166 (64% identical), RN7SKP189 (64% identical), RN7SKP162 (64% identical), and 284 more.